FTO (FTO alpha-ketoglutarate dependent dioxygenase)
Diseases named in the same sentence as FTO in open-access papers (continued):
Sharing a sentence is not in itself a finding about the gene and the disease.
Obesity (continued). "Having shown the relevance of FTO for the development of the metabolic syndrome in an animal model, which is supported by certain GWAS in humans, the question arises how FTO can be a target in the context of an anti-obesity therapy." (PMID 25144618, 2014). "The effect of FTO gene on obesity is mainly by increasing energy intake and reducing satiety sensation." (PMID 24466303, 2014). "FTO is a potential target for obesity, and various groups are working to develop selective inhibitors for FTO, both as functional probes and for target validation." (PMID 24489119, 2014). "We reported two new obesity-related FTO SNPs (rs7206790 and rs11644943) among Chinese school-age children." (PMID 25251416, 2014). "Nevertheless, this structural information provides a starting point for the successful development of FTO inhibitors that holds promise for developing therapeutic agents to treat obesity." (PMID 25251416, 2014). "The FTO over-expression level seems to be related to subcutaneous fat accumulation, obesity and oxidative stress and lipid deposition in the liver." (PMID 25367448, 2014). "The altered substrate utilization and sensing of dietary macronutrients highlight a critical role for FTO in regulating peripheral metabolism and provide mechanistic insights into how FTO contributes to obesity." (PMID 24847356, 2014). "Several other studies replicated FTO rs9939609 and rs8050136 with obesity and BMI in Chinese or Asians." (PMID 24879436, 2014). "More research needs to be conducted to clarify the role of RPGRIP1L and IRX3 in obesity and their relation to FTO." (PMID 25501432, 2014). "We only tested four SNPs in FTO gene due to its relationship with obesity, in a small sample, and think that a genome-wide scan in a much larger sample is warranted for more reliable inferences." (PMID 25628644, 2014). "Genetic variants of the FTO gene rs9939609 A/T and the MC4R gene rs17782313 C/T have been associated with obesity." (PMID 23849767, 2013). "In this regard, plasma leptin concentrations under conditions of severe obesity can exceed 100 ng/ml and it would therefore be of importance to determine cardiac FTO expression under more pronounced hyperleptinemic conditions." (PMID 24019958, 2013). "The association of six European obesity-related SNPs in or near FTO, NPC1, ENPP1, NEGR1, GNPDA2 and MC4R genes with risk of obesity was tested in 1,463 school-aged Mexican children (Ncases = 514; Ncontrols = 949)." (PMID 23375129, 2013). "Nonetheless, more in-depth studies are required to elucidate the biological role of FTO playing on the interaction of obesity and PCOS." (PMID 23840863, 2013). "The most extensively studied example of a gene × physical activity interaction in obesity is for the FTO locus, which was recently replicated in a meta-analysis comprising 240,000 persons." (PMID 23935507, 2013). "Recently, genome-wide association studies (GWAs) have identified polymorphisms in or close to the FTO and MAF gene to be associated with obesity." (PMID 23840443, 2013). "Along with the strong association of the FTO locus, we also detected association of the SNP rs2815752 near the NEGR1 gene with severe obesity." (PMID 23950990, 2013). "Subsequently, several other studies have consistently confirmed the association of a cluster of SNPs within the first intron of the FTO gene with obesity-related traits in several European, Asian and African populations." (PMID 23342142, 2013). "The importance of the 16q12.2/FTO locus for obesity-related traits was identified in genome-wide scans of Europeans." (PMID 23341774, 2013). "Following the GWAS obesity identification of FTO, two mouse models were used to investigate its biological function in vivo." (PMID 23360386, 2013). "Among these loci, the fat mass and obesity-associated (FTO) gene, which was first identified in a GWA study of diabetes in 2007, has the strongest influence on BMI and obesity." (PMID 23835106, 2013).
Obesity (continued). "The link between genetic variation in FTO and obesity was first described in a GWAS for type 2 diabetes and was later independently confirmed in different populations all over the world." (PMID 23300491, 2013). "After adjusting for age, sex and admixture, significant associations with obesity were found for 6 genes in the case-control study (ADIPOQ, FTO, TMEM18, INSIG2, FAIM2/BCDIN3 and BDNF)." (PMID 23950976, 2013). "Two common variants (near or in FTO and MC4R) alter diabetes risk mediated by a primary effect of obesity." (PMID 23997649, 2013). "The fat mass and obesity (FTO) gene has one of the strongest links with body mass index (BMI) in the human population." (PMID 23300482, 2013). "FTO, TMEM18 and INSIG2 variants showed the most significant associations with obesity in this population." (PMID 23950976, 2013). "Heterogeneity in effect sizes between class I/II and class III obesity was statistically significant only for FTO rs9939609 (Phet = 0.031) and borderline significant for MC4R rs17782313 (Phet = 0.050)." (PMID 23950976, 2013). "A genetic risk score constructed with the FTO, MC4R and six of the newly discovered loci performed poorly as a predictor of obesity and the explained variance of BMI was less than 1%." (PMID 24267414, 2013). "FTO is expressed in the hypothalamus, and inactivation of FTO in mice protects against obesity while over-expression leads to increased energy intake and obesity." (PMID 23589710, 2013). "We investigated cross-sectionally and longitudinally the relationship between FTO rs9939609 and obesity-related characteristics in the European children of the IDEFICS project and the interaction of this variant with a lifestyle intervention." (PMID 23155422, 2012). "Statistical and biological interactions with PA and diet modulate the effects of FTO and MC4R polymorphisms on obesity." (PMID 23284998, 2012). "The results also indicated that the effects of FTO on obesity, due to a reduction in sensitivity of the appetite control system, can start from a young age, and can even be modified during prenatal development." (PMID 22355368, 2012). "It is therefore possible that FTO mainly affects the amount of soft tissue, but appears to have less effect on metabolic markers relating to obesity, and WHR representing abdominal obesity." (PMID 22817777, 2012). "Among these genes, FTO has been repeatedly identified, and KCTD15, TMEM18, MTCH2, and NEGR1 have been considered to confer obesity risk through effects in the central nervous system." (PMID 22355368, 2012). "Prevalence of overweight/obesity at T0 and T1 and incidence over the two-year follow-up, according to FTO rs9939609 genotypes." (PMID 23155422, 2012). "So far, very limited data is available on the relationship between FTO gene and obesity in the Italian adult population." (PMID 22454631, 2012). "A few studies have also jointly analyzed the FTO and MC4R polymorphisms, describing their additive effects on obesity related variables." (PMID 23284998, 2012). "Considering the significant gene-diet interaction results that we have obtained for the FTO and MC4R loci, it would be interesting in future studies to analyze this interaction for other polymorphisms previously associated with obesity and/or diabetes." (PMID 23130628, 2012). "The FTO SNP rs9939609 and UCP-1 SNP rs6536991 demonstrated a statistically significant association with the obesity phenotype as measured by BMI (p= 0.04 and p< 0.0001 respectively)." (PMID 23134754, 2012). "As far as we know this is the first time that a statistically significant interaction between the aggregate score of the FTO and the MC4R polymorphisms and physical activity on BMI and obesity is reported." (PMID 23284998, 2012). "Studies have shown that FTO functions as a demethylase and predominantly affect obesity by influencing energy intake." (PMID 23091647, 2012).
Obesity (continued). "Thus, when physical activity was low, the FTO polymorphism and the aggregate score were significantly associated with higher obesity risk in carriers of the variant allele (a 17% per-allele increase; 95%CI: 7–27 and a 12% per-allele increase; 95%CI: 5–20 in the OR of obesity, respectively)." (PMID 23284998, 2012). "Our data are consistent with FTO rs9939609 and UCP-1 rs6536991 common variants as contributors to obesity in the Brazilian population." (PMID 23134754, 2012). "For the binary trait of obesity, we found 16 genome-wide significant signals within the FTO gene (strongest signal at rs17817449, P = 2.5×10−12)." (PMID 21552555, 2011). "Several independent genome-wide association studies recently identified two common polymorphisms, FTO rs9939609 and MC4R rs17782313, that are linked to increased body weight and obesity." (PMID 21347432, 2011). "Our results indicate an early impact of maternal obesity to up-regulate hypothalamic FTO, which correlated with increased subsequent intake of palatable HFD." (PMID 21980407, 2011). "It has also been demonstrated that inactivation of the FTO gene in mice reduced white adipose tissue mass and adipocyte size, and protected from diet induced obesity." (PMID 21687707, 2011). "QTDT analysis further revealed that five SNPs in FTO and two in MC4R were significantly associated with obesity in the PCOS families." (PMID 21283731, 2011). "Furthermore, results from twin research on adults indicate that the genetic influence on obesity and fat mass decreases with increasing age, an observation that both can be explained by a strengthened lifestyle influence at old age but also partially by survival bias associated with the FTO gene." (PMID 21637715, 2011). "By combining data from 218,166 adults from 45 studies, we confirm that PA attenuates the influence of FTO variation on BMI and obesity." (PMID 22069379, 2011). "Of note, FTO was the only previously identified and consistently replicated obesity locus we identified." (PMID 22022282, 2011). "Larger GWA meta-analysis, through the Genetic Investigation of Anthropometric Trait (GIANT) Consortia and deCODE followed reporting 8 novel obesity loci, as well as confirming the MC4R and FTO associations." (PMID 21466928, 2011). "The association of the two major contributors to polygenic obesity (SNP rs17782313 near MC4R and SNP rs1421085 / rs9939609 in FTO) with food intake / food behavior-related endophenotypes has been well documented in the literature." (PMID 22043165, 2011). "This is perhaps best illustrated in the original study that reported on the significance of FTO for obesity." (PMID 22069377, 2011). "For example, FTO is the major contributor to polygenic obesity and mice down or over-expressing FTO are resistant or prone to develop obesity." (PMID 22043165, 2011). "Studies at different developmental stages are required to fully understand the role of FTO in the development of obesity and the regulation of energy homeostasis." (PMID 21980407, 2011). "This approach has been successfully used in the obesity arena following the identification of FTO as a major contributor to polygenic variation." (PMID 22043165, 2011). "Carriage of the FTO rs9939609 A and MC4R rs17782313 C alleles was estimated to increase the risk of obesity by 31% and 12%, respectively." (PMID 21347432, 2011). "FTO is a well studied gene that is abundantly expressed in the hypothalamus and adenohypophysis and related to food intake and obesity." (PMID 21787428, 2011). "With the development of high-throughput genotyping techniques and the implementation of genome-wide association studies (GWAS), common variations, such as those in FTO and MC4R, have been associated with obesity and body mass index (BMI)." (PMID 21552555, 2011). "Other genes have also been associated with obesity in the general population, most notably the melanocortin-4-receptor (MC4R) and the fat mass and obesity-associated (FTO) genes." (PMID 21298202, 2011).
Obesity (continued). "Taken together, data from the literature suggest that FTO and NAMPT represent two novel candidates potentially involved in the pathophysiology of obesity and associated metabolic disorders." (PMID 21687707, 2011). "To this end we examined the impact of maternal obesity and early life overnutrition induced by litter size reduction on FTO expression in the hypothalamus." (PMID 21980407, 2011). "Together, these findings support a functional role for FTO in the development of obesity on the central and/or peripheral level." (PMID 21687707, 2011). "We also re-identified variants in or near FTO, MC4R, and TMEM18 to be associated with extreme obesity." (PMID 20421936, 2010). "Since the discovery of the FTO signal, additional GWAS have succeeded in identifying many additional novel obesity loci." (PMID 20381893, 2010). "Moreover, using a single genetic variant of given gene (FTO rs9939609) in present study was also a limitation, which may be in linkage disequilibrium with polymorphisms of other nearby genes that actually contributed to the development of obesity." (PMID 20858286, 2010). "In this study, the relationship between diabetes, four previously reported FTO SNPs, and obesity was examined in African-American and white individuals enrolled in the large prospective Atherosclerosis Risk in Communities (ARIC) study." (PMID 20502638, 2010). "Simultaneously a third study identified the effect of FTO on obesity while testing for population stratification." (PMID 20377915, 2010). "When the obesity causal genes were overlapped with the fasted and fed networks, 7 genes (ADA, BBS5, CBL, CCND3, FASN, FTO and SCARB1) overlapped with PER1's downstream genes in the fed network (Fisher's Exact Test p-value = 0.037)." (PMID 20168994, 2010). "We have found associations (with p values less than 0.05) for SGA with the diabetes related SNP in KCNJ11 and the obesity related SNPs in FTO, PFKP, PTER, SEC16B and BDNF." (PMID 20712903, 2010). "We observed that genetic variants in or near FTO, MC4R, TMEM18, SDCCAG8, and TNKS/MSRA were robustly associated with early-onset obesity." (PMID 20421936, 2010). "Preliminary evidence for gene-lifestyle interaction has come from studies on the FTO locus, the firstly GWA-identified obesity-susceptibility locus with the largest influence on BMI and obesity risk to date." (PMID 20824172, 2010). "Recent genome wide association scans have identified regions in the FTO gene and variants telomeric to the MC4R gene to be associated with obesity." (PMID 19183461, 2009). "The study by Grant and colleagues described a correlation between a SNP (rs3751812, P = 0.017, OR = 1.3, 95%CI 1.1–1.6) in the FTO gene and obesity in young African-Americans (578 obese vs 1424 controls)." (PMID 19265514, 2009). "The current project was designed to characterize the relationship between FTO and obesity through feeding models, molecular analyses and functional neuroanatomy in mice." (PMID 19860904, 2009). "Our study provides direct evidence that FTO directly affects fat mass and thus is likely to have a role in human obesity." (PMID 19680540, 2009). "Our data strongly suggest that FTO, the first gene contributing to common forms of human obesity, plays a significant role in mechanisms responsible for the regulation of energy-related eating behavior." (PMID 19860904, 2009). "Recent genome-wide association studies have identified two genes (FTO and near MC4R) that were unequivocally associated with body mass index (BMI) and obesity." (PMID 20017980, 2009). "The consistency of replication across several samples of Caucasian origin and lately in other ethnic samples has considerably strengthened the important contribution of FTO to obesity." (PMID 18682847, 2008). "Knowledge of the function of FTO is crucial to guide the search for a mechanism relating this gene to obesity." (PMID 17996046, 2007).
Obesity (continued). "FTO, although identified through a T2D GWAS, has already been established as a robustly replicating obesity locus." (PMID 17897328, 2007). "Our GWA for extreme early onset obesity substantiates that variation in FTO strongly contributes to early onset obesity." (PMID 18159244, 2007). "This insight should help to guide experiments to clarify the mechanisms by which FTO relates to obesity and to accelerate the discovery of novel molecular therapies for this condition." (PMID 17996046, 2007). "Eleven of the best 15 markers were subsequently genotyped in 644 independent obesity families based on at least one young obese index patient; of the six positive FTO SNPs belonging to the same LD block, we genotyped only the two SNPs with the lowest p-values." (PMID 18159244, 2007). "Bioinformatic analyses revealed a negative correlation between fat mass and obesity-associated protein (FTO) and LUR1 expression and abundant m6A sites within the LUR1 mRNA strand." (PMID 42277600, 2026). "Furthermore, after adjusting for sex and total energy intake, dietary intake of added sugar was negatively associated with the FTO and SREBP1 expression in PBMCs from children with obesity." (PMID 40806129, 2025). "Paradoxically, the average FTO expression level was also elevated in the obesity group." (PMID 40869388, 2025). "Moreover, Ftolox/lox/Agrp-Cre mice were resistant to high-fat diet (HFD)-induced obesity, suggesting that FTO expression is necessary for that phenotype." (PMID 40634669, 2025). "Genetic factors that influence obesity are the fat mass and obesity (FTO) genes." (PMID 39981080, 2025). "Further studies have documented the impact of the FTO genotype on body weight and obesity traits." (PMID 40630163, 2025). "Additionally, the Alpha-Ketoglutarate Dependent Dioxygenase (FTO) gene, which is known as the fat mass and obesity-associated gene, was also identified." (PMID 39944650, 2025). "First, they demonstrate that FTO variants exert effects independent of obesity, interact with environmental exposures such as smoking, and manifest through both additive and supra-additive mechanisms." (PMID 41303403, 2025). "The role of the FTO locus in homeostatic appetite regulation in individuals who have already developed obesity, therefore, remains unclear." (PMID 39792913, 2025). "Similarly, Alpha-Ketoglutarate-Dependent Dioxygenase (FTO) is an mRNA demethylase studied for its role in the regulation of obesity." (PMID 40963109, 2025). "Genetic factors such as FTO, MC4R, and LEPR polymorphisms may further influence susceptibility to obesity." (PMID 41228239, 2025). "Single nucleotide polymorphisms such as FTO rs9939609, MC4R rs17782313, and BDNF rs6265, have been consistently associated with elevated body weight and an increased risk of obesity across diverse populations through their roles in appetite regulation, satiety, and energy balance." (PMID 40423790, 2025). "FTO genes have been identified as major genetic risks at obesity loci." (PMID 39981080, 2025). "While several studies have shown a strong association between fat mass and obesity-associated (FTO) polymorphisms and obesity risk, only a limited number have investigated the genetic differences of FTO between MASLD and non-MASLD individuals." (PMID 40864759, 2025). "Our findings contribute to this evolving evidence by suggesting that enhanced gastric FTO expression may coexist with elevated circulating adiponectin, consistent with the concept of the adiponectin paradox and the metabolically healthy obesity phenotype." (PMID 41423640, 2025). "For example, variants of the fat mass and obesity-associated gene (FTO) and melanocortin 4 receptor (MC4R) genes have been shown to be associated with higher BMI and obesity measures, with urban living amplifying the effect of the FTO polymorphism." (PMID 40944253, 2025). "This suggests the involvement of FTO in the pathophysiology of obesity-related adiposity." (PMID 41423640, 2025).